GRWD1 (glutamate rich WD repeat containing 1)
Description:
Histone binding protein that regulates chromatin dynamics and loading of minichromosome maintenance (MCM) complex at replication origins, possibly by promoting chromatin openness. Plays a role in ribosomal biogenesis.
Synonyms: GRWD; WDR28; RRB1; CDW4; DIAR14
Tractability: PROTAC: ubiquitination databases record sites on it; its protein half-life has been measured.
Gene: Protein-coding gene on chromosome 19 (48,445,824 to 48,457,022, forward strand). Ensembl gene ENSG00000105447.
Subcellular location: Nucleus, nucleolus; Nucleus; Chromosome
Subcellular location (Human Protein Atlas): Nucleoli; Nucleoli rim; Nucleoplasm
Gene Ontology:
Molecular function: chromatin binding; DNA replication origin binding; histone binding; protein binding; RNA binding
Biological process: DNA replication; nucleosome assembly; nucleosome disassembly; ribosome biogenesis
Cellular component: chromosome; nucleolus; nucleoplasm; nucleus; protein-containing complex
Genetic constraint (gnomAD): Loss-of-function variants: 29 observed, 45.91 expected, observed/expected ratio (o/e) 0.63, 90% interval 0.47 to 0.86. The upper end of that interval is the gene's LOEUF score, 0.86, which puts it in group 3 of 6, group 1 being the genes least tolerant of losing a copy. Missense variants: 572 observed, 612.84 expected, observed/expected ratio (o/e) 0.93, 90% interval 0.87 to 1. Synonymous variants: 256 observed, 251.63 expected, observed/expected ratio (o/e) 1.02, 90% interval 0.92 to 1.13.
Homologues: Orthologues: chimpanzee GRWD1 (99% identical), macaque GRWD1 (98% identical), pig GRWD1 (94% identical), rabbit GRWD1 (93% identical), rat Grwd1 (92% identical), mouse Grwd1 (91% identical), dog GRWD1 (91% identical), tropical clawed frog grwd1 (68% identical), zebrafish grwd1 (59% identical), Drosophila melanogaster l(2)09851 (52% identical), Caenorhabditis elegans grwd-1 (43% identical). Paralogues in human: ERCC8 (18% identical), GEMIN5 (17% identical), RBBP4 (16% identical), RBBP7 (15% identical), PEX7 (14% identical), WDR24 (13% identical), WDR59 (12% identical), WDR73 (12% identical), WDR77 (12% identical).
Diseases named in the same sentence as GRWD1 in open-access papers:
GRWD1 is named in the same sentence as 34 diseases in open-access papers, as found by Europe PMC text mining. Sharing a sentence is not in itself a finding about the gene and the disease. The quoted sentences say what the papers report.
breast carcinoma (3 papers, 2021 to 2022). "Patients with a higher expression level of GRWD1 had a worse prognosis for LGG, lung adenocarcinoma (LUAD), breast cancer (BC), SARC, and SKCM." (PMID 34933446, 2021). "In reviewing the literature, no data were found on the association of breast cancer with PCGF1, RNF123, GRWD1, USP30, ATXN3L, and PARP11." (PMID 36685836, 2022).
lung carcinoma (3 papers, 2008 to 2025). "The high expression level of GRWD1 in lung cancer tissue was associated with a poor prognosis of patients with first progression (FP) (P = 0.0016), confirming shorter OS (P < 0.001) and postprogression survival (PPS) (P < 0.001)." (PMID 34616846, 2021). "In lung cancer, enhanced GRWD1 expression is observed in NSCLC tissues, and its high expression is strongly linked to a large tumor size and lymph node metastasis, whereas it is inversely linked to tumor differentiation and survival outcomes." (PMID 41031217, 2025). "Five prognostic genes, including HPSE, DENND1C, GRWD1, HLA‐DQA1, and PDXK, were identified to further develop a risk signature, which exhibited moderate power for forecasting the prognosis of lung cancer patients in training, testing, and validation sets." (PMID 41031217, 2025).
colon carcinoma (2 papers, 2021 to 2022). "The CPTAC dataset was used to examine differences in GRWD1 protein levels in 7 tumor tissues, and it was revealed that GRWD1 protein levels were higher in clear cell renal cell carcinoma (ccRCC), colon cancer, and LUAD than in adjacent normal tissues (P < 0.01)." (PMID 34616846, 2021).
colorectal cancer (2 papers, 2020 to 2021). A primary or metastatic malignant neoplasm that affects the colon or rectum. "The overexpression of GRWD1 is also associated with poor prognosis of patients with non-small cell lung cancer and colorectal cancer." (PMID 34616846, 2021).
bladder cancer (1 paper, 2024). "(A) Relative enrichment of circHIPK3 levels or ACTB mRNA between IP and input for the three RNA-binding proteins (RBPs) GRWD1, IGF2BP1, and IGF2BP2 in the bladder cancer cell line FL3." (PMID 39041323, 2024).
heart failure (1 paper, 2022). Inability of the heart to pump blood at an adequate rate to meet tissue metabolic requirements. "Most characteristic genes presented negative correlations to the abundance of immune cells in heart failure, but GRWD1 was positively linked to most immune cell types, indicating their functions in mediating cardiac inflammation." (PMID 36313471, 2022).
non-small cell lung carcinoma (1 paper, 2021). A group of at least three distinct histological types of lung cancer, including non-small cell squamous cell carcinoma, adenocarcinoma, and large cell carcinoma. "In non-small cell lung cancer, GRWD1 can activate the cell proliferation and migration abilities via the Notch pathway." (PMID 34616846, 2021).
ovarian carcinoma (1 paper, 2021). A malignant neoplasm originating from the surface ovarian epithelium. "In addition, a low expression level of GRWD1 in ovarian cancer tissue indicated longer OS (P = 0.0075) and RFS (P = 0.039), while shorter PPS (P = 0.021)." (PMID 34616846, 2021).
uveal melanoma (1 paper, 2021). A melanoma derived from melanocytes of the uveal tract. "The expression level of GRWD1 was also positively correlated with the MSI in LIHC (P = 0.0022), uveal melanoma (UVM; P = 0.045), KIRC (P = 3.59e − 06), and SARC (P = 6.71e − 07) tissues, whereas it was negatively correlated with the MSI in READ tissue (P = 0.0022)." (PMID 34616846, 2021).
tumor (8 papers, 2017 to 2026). "Spearman's correlation analysis was used to find out the correlation between the expression level of GRWD1 and predictive biomarkers, such as tumor mutation burden (TMB) and microsatellite instability (MSI)." (PMID 34616846, 2021). "Knockdown of GRWD1 inhibited cell proliferation, cellular transformation, and tumor formation and caused downregulation of global H3K4me3 mark in KMM cells." (PMID 34933446, 2021). "The expression level of GRWD1 in human cancer tissues was analyzed using the Tumor Immune Evaluation Resource (ver." (PMID 34616846, 2021). "As another novelty of the current research, a potential correlation was identified between the expression level of GRWD1 in tumor tissues in TCGA and MSI/TMB." (PMID 34616846, 2021). "In the TCGA database, we used TIMER2 to investigate the differential expressions of GRWD1 in 33 tumor tissues." (PMID 34616846, 2021). "The results of Kyoto Encyclopedia of Genes and Genomes (KEGG) pathway enrichment analysis revealed that “ubiquitin mediated proteolysis,” “spliceosome,” and “nucleotide excision repair” were involved in the effect of GRWD1 expression on tumor pathogenesis." (PMID 34616846, 2021). "For protein expression analysis, we used the CPTAC module provided by the UALCAN portal to compare the total protein and phosphorylated protein level of GRWD1 in adjacent normal and tumor tissues." (PMID 34616846, 2021). "The cBioPortal presented the genetic alterations of GRWD1 in different tumor samples in the TCGA cohort." (PMID 34616846, 2021). "We utilized the CPTAC dataset to compare the phosphorylation levels of GRWD1 in adjacent normal and tumor tissues." (PMID 34616846, 2021). "The expression level of GRWD1 in KICH, KIRP, and KIRC tissues showed an opposite trend, and the expression level of GRWD1 was correlated to only the KIRC tumor stage." (PMID 34616846, 2021). "Overall, the expression level of GRWD1 varied in different types of cancer, confirming tumor heterogeneity." (PMID 34616846, 2021). "Because the high expression of GRWD1 in tumor cells can promote tumor cell growth, the aberrant methylation of the GRWD1 gene can inhibit its activity." (PMID 30498398, 2018). "We further examined the effect of GRWD1 knockdown on tumor formation of KMM cells in nude mice." (PMID 34933446, 2021). "The results of bioinformatics analysis indicated GRWD1 as a promising biomarker for detection, prognosis, and therapeutic assessment of diverse types of cancer, and GRWD1 could act as a tumor suppressor in KIRC." (PMID 34616846, 2021). "In addition, the results of the current research, for the first time, revealed that the expression level of GRWD1 in some tumor tissues was correlated to the level of immune infiltration of endothelial cells and cancer-associated fibroblasts." (PMID 34616846, 2021). "Concerning the high expression level of GRWD1 in tumor tissues, the expression level of GRWD1 in only LUAD tissue could predict OS." (PMID 34616846, 2021). "The tumor suppression potential of GRWD1 in KRIC and its correlation with MSI and the CD274 gene may be significant for the therapy of KRIC." (PMID 34616846, 2021). "Multivariate analysis confirmed tumor multiplicity (p = 0.013), TNM stage (p < 0.001), and GRWD1 expression (p = 0.021) as independent predictors in the patients." (PMID 41234500, 2026). "Univariate analysis revealed tumor multiplicity (p < 0.001), Child-Pugh grade (p = 0.046), TNM stage (p < 0.001), and GRWD1 expression (p = 0.005) as significant prognostic factors of survival in HCC patients." (PMID 41234500, 2026). "We then analyzed the correlation between the expression level of GRWD1 and TMB/MSI in all tumor samples from TCGA." (PMID 34616846, 2021). "Additional genes with potential tumor suppressor function that have been shown to be involved in MCPyV integration include PTPRG, GRWD1, and XRCC4." (PMID 32878339, 2020).
tumor (continued). "In the TACE-treated subgroup, while age, tumor multiplicity, and TNM stage showed prognostic value consistently, GRWD1's effect was not statistically significant, likely due to limited sample size." (PMID 41234500, 2026).
cancer (5 papers, 2015 to 2021). A tumor composed of atypical neoplastic, often pleomorphic cells that invade other tissues. "In KIRP and LGG, the expression level of GRWD1 was also positively correlated with infiltration of cancer-associated fibroblasts, while it was negatively correlated with TGCT." (PMID 34616846, 2021). "The results of survival analysis showed that the expression level of GRWD1 was significantly associated with overall survival in six types of cancer and disease-free survival (DFS) in three types of cancer." (PMID 34616846, 2021). "Indeed, our results show that GRWD1 dysregulation is associated with poor prognosis of patients in several types of cancer, including brain lower-grade glioma (LGG), mesothelioma (MESO), and skin cutaneous melanoma (SKCM)." (PMID 34933446, 2021). "We used the TCGA database to study the relationship between the expression level of GRWD1 and the survival of patients with different types of cancer." (PMID 34616846, 2021). "We utilized the “immune” module provided on the TIMER2 website to explore the relationship between the expression level of GRWD1 and immune infiltration in all types of cancer in TCGA." (PMID 34616846, 2021). "We used the UALCAN website to find out the DNA methylation level of GRWD1 in cancer tissues that was significantly downregulated in TGCT (P < 0.0001)." (PMID 34616846, 2021). "The expression level of GRWD1 was significantly correlated to the prognosis of some types of cancer, TMB/MSI, and immune checkpoint-related genes." (PMID 34616846, 2021). "We also found that the expression level of GRWD1 was positively correlated with the expression levels of immune checkpoint-related genes in most types of cancer." (PMID 34616846, 2021). "We divided cancer patients into high expression level and low expression level groups according to the expression level of GRWD1." (PMID 34616846, 2021). "Interestingly, GRWD1 is upregulated in KSHV-transformed cells, and high expression of GRWD1 predicts poor patient survival in numerous types of cancer." (PMID 34933446, 2021). "In order to explore the expression level of GRWD1 in various types of cancer by pancancer analysis, the present study was conducted using bioinformatics tools, and it was found that GRWD1 was highly expressed in almost all types of cancer." (PMID 34616846, 2021). "Further research is required to indicate whether GRWD1 can play a role in the pathogenesis of different types of cancer through some common molecular mechanisms." (PMID 34616846, 2021). "Therefore, we utilized the TIMER, CIBERSORT, CIBERSORT-ABS, TIDE, xCell, MCPcounter, quanTIseq, and EPIC algorithms in TIMER2 to explore the correlation between different cell infiltration levels and the expression levels of GRWD1 in multiple types of cancer." (PMID 34616846, 2021). "However, previous studies limited the evaluation of GRWD1 to few types of cancer, and its role in other types of cancer has still remained elusive." (PMID 34616846, 2021). "The difference in the expression level of GRWD1 in different types of cancer may reflect its different functions and mechanisms." (PMID 34616846, 2021). "GRWD1 is a multifunctional protein, which is overexpressed in cancer cells." (PMID 33287884, 2020). "This may be due to the relatively high basal expression levels of the initiation proteins and GRWD1 in cancer-derived HeLa cells." (PMID 25990725, 2015). "Furthermore, we have observed GRWD1 overexpression in cancer cells, also suggesting its importance in promotion of cell growth." (PMID 25990725, 2015).
cancer (continued). "Since a higher expression level of GRWD1 is associated with a worse prognosis of 5 types of cancer, especially SARC, which is similar to KS and the KMM tumor, and its epigenetic role in cancer is largely unknown, we chose to further investigate GRWD1’s role in KSHV-induced cellular transformation." (PMID 34933446, 2021). "Therefore, GRWD1 has broad application prospects for the treatment of some types of cancer." (PMID 34616846, 2021). "We found that the expression level of GRWD1 was positively correlated with the expression levels of immune checkpoint-related genes (CD274, CTLA4, HAVCR2, LAG3, PDCD1, PDCD1LG2, SIGLEC15, and TIGIT) in most types of cancer, especially in STAD." (PMID 34616846, 2021). "There was a positive relationship between the expression level of GRWD1 and immune cell infiltration in several types of cancer, and the expression level of GRWD1 was also positively correlated with TMB, MSI, and DNA methylation in some types of cancer." (PMID 34616846, 2021). "In summary, using pancancer analysis of GRWD1, we found that the expression level of GRWD1 was correlated to the clinical prognosis, protein phosphorylation level, immune cell infiltration, immune checkpoint-related genes, TMB, and MSI in diverse types of cancer." (PMID 34616846, 2021). "It was found that the expression level of GRWD1 was only statistically significant in KIRC tissues (P < 0.05), rather than in other types of cancer." (PMID 34616846, 2021).
GRWD1 also shares sentences with these, for which no sentence is quoted: gastric cancer (2 papers); acute myeloid leukemia (1); cervical squamous cell carcinoma (1); clear cell renal cell carcinoma (1); diffuse large B-cell lymphoma (1); endocervical adenocarcinoma (1); glioblastoma multiforme (1); hepatocellular carcinoma (1); infection (1); Insulin resistance (1); ischaemic stroke (1); liver cancer (1); lung adenocarcinoma (1); melanoma (1); ovarian serous cystadenocarcinoma (1); pancreatic adenocarcinoma (1); paraganglioma (1); pheochromocytoma (1); skin cutaneous melanoma (1); testicular germ cell tumor (1); thymoma (1); uterine carcinosarcoma (1); uterine corpus endometrioid carcinoma (1).